SLC6A20 (solute carrier family 6 member 20)
Description:
Mediates the Na(+)- and Cl(-)-dependent uptake of imino acids such as L-proline, N-methyl-L-proline and pipecolate as well as N-methylated amino acids. Also transports glycine, regulates proline and glycine homeostasis in the brain playing a role in the modulation of NMDAR currents.
Synonyms: SIT1; XT3; XTRP3; IMINO
Tractability: Small molecule: a structure with a bound ligand is known; it belongs to a druggable protein family. Antibody: its Gene Ontology location is reachable by antibodies, with high confidence; UniProt places it where antibodies can reach, with medium confidence; UniProt predicts a signal peptide or a membrane-spanning region.
Gene: Protein-coding gene on chromosome 3 (45,755,449 to 45,796,591, reverse strand). Ensembl gene ENSG00000163817.
Subcellular location: Apical cell membrane
Pathways (Reactome):
Disease: Variant SLC6A20 affecting amino acid transport contributes towards hyperglycinuria (HG) and iminoglycinuria (IG); Variant SLC6A20 affecting neurotransmitter transport contributes towards hyperglycinuria (HG) and iminoglycinuria (IG)
Transport of small molecules: Amino acid transport across the plasma membrane; SLC-mediated transport of neurotransmitters
Gene Ontology:
Molecular function: amino acid transmembrane transporter activity; L-proline transmembrane transporter activity; neutral L-amino acid transmembrane transporter activity; proline:sodium symporter activity; protein binding; solute:sodium symporter activity; amino-acid betaine transmembrane transporter activity; glycine transmembrane transporter activity; L-isoleucine transmembrane transporter activity; transmembrane transporter activity
Biological process: amino acid transport; glycine import across plasma membrane; glycine transport; L-proline import across plasma membrane; proline import across plasma membrane; proline transport; amino acid import across plasma membrane; amino-acid betaine transport; L-isoleucine import across plasma membrane; neurotransmitter transport; sodium ion transmembrane transport; transport across blood-brain barrier
Cellular component: apical plasma membrane; plasma membrane; postsynaptic membrane; membrane
Genetic constraint (gnomAD): Loss-of-function variants: 74 observed, 68.06 expected, observed/expected ratio (o/e) 1.09, 90% interval 0.9 to 1.32. The upper end of that interval is the gene's LOEUF score, 1.32, which puts it in group 5 of 6, group 1 being the genes least tolerant of losing a copy. Missense variants: 725 observed, 805.81 expected, observed/expected ratio (o/e) 0.9, 90% interval 0.85 to 0.96. Synonymous variants: 347 observed, 346.52 expected, observed/expected ratio (o/e) 1, 90% interval 0.92 to 1.09.
Homologues: Orthologues: chimpanzee SLC6A20 (99% identical), macaque SLC6A20 (97% identical), mouse Slc6a20a (92% identical), dog SLC6A20 (92% identical), rat Slc6a20a (91% identical), rabbit SLC6A20 (88% identical), mouse Slc6a20b (87% identical), rat Slc6a20b (86% identical), guinea pig Slc6a20 (85% identical), pig SLC6A20 (84% identical), tropical clawed frog slc6a20 (74% identical). Paralogues in human: SLC6A18 (47% identical), SLC6A19 (47% identical), SLC6A15 (43% identical), SLC6A17 (42% identical), SLC6A12 (35% identical), SLC6A8 (35% identical), SLC6A9 (35% identical), SLC6A7 (34% identical), SLC6A13 (34% identical), SLC6A5 (34% identical), SLC6A11 (33% identical), and 6 more.
Diseases named in the same sentence as SLC6A20 in open-access papers:
SLC6A20 is named in the same sentence as 41 diseases in open-access papers, as found by Europe PMC text mining. Sharing a sentence is not in itself a finding about the gene and the disease. The quoted sentences say what the papers report.
COVID-19 (62 papers, 2020 to 2025). A disease caused by infection with severe acute respiratory syndrome coronavirus 2. "Greater methodological transparency would help contextualize the role of SLC6A20 within the broader network of genes implicated in COVID-19 pathogenesis." (PMID 40543387, 2025). "The pairwise combination rs67579710 THBS3, THBS3-AS1 × rs17713054 SLC6A20-LZTFL1 was a priority in determining susceptibility to severe COVID-19 (it was included in four of the top five most significant SNP-SNP interaction models)." (PMID 39175753, 2024). "SNP rs17078346 SLC6A20-LZTFL1 (risk allele C) also was associated with the increased the risk of severe COVID-19 in our study, exclusively in obese patients." (PMID 39175753, 2024). "In this study, rs73064425 and its two colocalized genes, LZTFL1 and SLC6A20 were found to be associated with COVID-19 severity." (PMID 37160831, 2023). "Given that the COVID-19 disease islinked with a cytokine storm and inflammatory associated complications, the expression of SLC6A20 genewas investigated in various immune cells." (PMID 37041751, 2023). "GEPIA and TIMER2.0 databaseswere used to determine the correlation between SLC6A20 and COVID-19-associated genes." (PMID 37041751, 2023). "Taken together, these findings indicated a potential involvementof SLC6A20 with COVID-19 susceptibility in differenttypes of human cancers via the association between SLC6A20 and the ACE2 homologue TMEM27." (PMID 37041751, 2023). "In conclusion, our study provides a systematic analysisof COVID-19 causal gene SLC6A20 in pan-cancer samples." (PMID 37041751, 2023). "rs73064425, associated with COVID-19 severity, was found to be colocalized with eQTLs for two genes, SLC6A20 and LZTFL1, with a posterior probability > 0.75." (PMID 37160831, 2023). "Detected lead SACM1L rs73060324 variant highly correlates with rs17279437 missense variant (r2 = 0.88) located in the SLC6A20 gene, a potential causative candidate which has been previously associated with COVID-19." (PMID 35910207, 2022). "Within the same risk-gene cluster in chromosome 3, we also detected two SLC6A20 variants, segregating with COVID-19 positive status." (PMID 36228008, 2022). "Recently identified as a putative causal gene modulating COVID-19 severity, SLC6A20 – also known as SIT1 – is a high-affinity luminal L-proline transporter highly expressed in lung epithelial cells." (PMID 35021853, 2022). "In summary, the potential COVID-19 severity associated gene, SLC6A20, and other amino acid transporters known to interact with ACE2 functionally converge with ACE2, B1R and mir200c signaling at the SNARE complex." (PMID 39086962, 2022). "In this work, we detected the clinical significance of IFNAR2 (2 SNPs), SLC6A20 (1 SNP) with respect to COVID-19 susceptibility and ADAM17 (2 SNPs), TMPRSS2 (1 SNP), TYK2 (1 SNP), DPP9 (1 SNP) with respect to the severity of the disease." (PMID 36292769, 2022). "We suggest that genetic variants near SLC6A20 affect the severity of COVID-19 symptoms due to interactions of SLC6A20 with ACE2." (PMID 33757938, 2021). "Significantly, SLC6A20 is at the peak of the strongest of two genome-wide association study loci for undesirable COVID-19 outcomes." (PMID 33757938, 2021). "Two loci associated with respiratory failure in COVID-19 were found, one of which was the GA-G insertion-deletion variant in locus 3p21.31 that is composed of six genes (SLC6A20, LZTFL1, CCR9, FYCO1, CXCR6, and XCR1)." (PMID 33791232, 2021). "In conclusion, we detected three rare and four ultrarare variants in four COVID-19-related genes, SLC6A20, LZTFL1, XCR1 and FURIN, that are present only in the Brazilian dataset and predicted to affect protein function." (PMID 33824725, 2021). "Furthermore, rs2531743 in the SLC6A20 gene was associated with long-term neurological complaints after recovery from COVID-19 illness (β = 1.99, p = 0.045)." (PMID 36675784, 2023).
COVID-19 (continued). "Since SLC6A20 gene was the only geneindependently identified in these two studies for COVID-19 risk, wehave focused on SLC6A20 in human tumor samples toinvestigate SLC6A20 expression in human pan-cancersamples and its association with SARS-CoV-2-related genes and immuneinfiltration." (PMID 37041751, 2023). "Collectively, our results suggest that SLC6A20 might be involved in the increased susceptibilityof cancer patientsto COVID-19." (PMID 37041751, 2023). "In addition, SLC6A20 expressionwas positively correlated with COVID-19-associated genes, ACE2, TMPRSS2,and TMPRSS4, in a number of tumor samples." (PMID 37041751, 2023). "In particular, a GWAS study on Italian and Spanish patients identified two susceptible loci of severe COVID-19 including one locus on chromosome 3 with multiple genes included (SLC6A20, LZFTL1, CCR9, CXCR6, XCR1, FYCO1), and the other on chromosome 9 that defines the ABO blood types." (PMID 36292769, 2022). "Interestingly, genomewide association study of severe COVID-19 identified a genetic susceptibility locus on 3p21.31 containing 6 genes, and recent data suggested SLC6A20 as one of the most likely gene candidates accounting for the association at this locus." (PMID 35705608, 2022). "The first GWAS analysis with 1980 patients with COVID-19 identified two loci associated with the most severe forms of COVID-19: one locus was 3p21.31, which includes the genes SLC6A20, LZTFL1, CCR9, FYCO1, CXCR6, and XCR1, while the other was 9q34.21, including the ABO blood group." (PMID 35455670, 2022). "The hypothesis-free approach of genome-wide association of hospitalized COVID-19 vs. the population highlighted SLC6A20 with genome-wide significance on chromosome 3 locus." (PMID 34512723, 2021). "Importantly, SLC6A20 is at the peak of a genome-wide association study for poor outcomes from COVID-19." (PMID 33757938, 2021). "Considering that SLC6A20 expression is positively associated with infiltrating neutrophils and immune-related signatures, the downregulation of this gene through exercise may further contribute to the mitigation of COVID-19 severity." (PMID 39175753, 2024). "In addition to ABO blood type, receptors, and immune genes, GWAS studies on COVID-19 have revealed the association of SLC6A20 (rs2271616), LZTFL1 (rs10490770, rs11385942, rs73064425), and DPP9 (rs2109069) genes with respiratory failure caused by COVID-19 infection and critical illness." (PMID 36292769, 2022). "Finally, the AncestryDNA COVID-19 host genetic study identified COVID-19 genetic associations with SLC6A20, LZTFL1 variants on the chromosome, ABO locus on chromosome 9 and a novel association on chromosome 11 that includes Polypeptide N-Acetylgalactosaminyltransferase 18 (GALNT18)." (PMID 34575070, 2021). "In summary, the current body of evidence supports a significant role for SLC6A20 in influencing the clinical course of COVID-19." (PMID 40543387, 2025). "Positioned within a genetic cluster that includes other functionally relevant genes, SLC6A20 is believed to exert a significant influence on disease progression, suggesting its potential as a therapeutic target for mitigating severe COVID-19 outcomes." (PMID 40543387, 2025). "A severe COVID-19 GWAS Group has identified genetic variants linked to genes such as SLC6A20, LZTFL1, CCR9, FYCO1, CXCR6, and XCR1 in patients experiencing respiratory failure due to COVID-19." (PMID 40143318, 2025). "We did not observe changes in the expression of any of the six genes clustered in the locus associated with respiratory failure in patients with COVID-19 (CCR9, SLC6A20, LZTFL1, CXCR6, XCR1, FYCO1)." (PMID 40722786, 2025). "The identification of SLC6A20 as a key determinant of COVID-19 severity carries important implications for disease management and the development of targeted therapies." (PMID 40543387, 2025).
COVID-19 (continued). "Upon the analysis of clinical characteristics among hospitalized COVID-19 patients, it was observed that rs17713054 SLC6A20-LZTFL1 (p = 0.006), rs12610495 DPP9 (p = 0.01), and rs17078346 SLC6A20-LZTFL1 (p = 0.01) were found to be linked with increased BMI." (PMID 39175753, 2024). "In the present study, we replicated associations of the rs17713054 SLC6A20-LZTFL1, rs17078346 SLC6A20-LZTFL1, rs12610495 DPP9 and rs7949972 ELF5 with severe COVID-19 within the Caucasian population of Central Russia." (PMID 39175753, 2024). "We replicated two loci identified by the HGI for COVID-19 severity: the LZTFL1/SLC6A20 locus on chromosome 3 and the FOXP4 locus on chromosome 6 (the latter with a variant significant at P < 5E-8)." (PMID 38517939, 2024). "A recent study developed by our research group investigated genetic variants present in the genes SLC6A20, LZTFL1, CCR9, FYCO1, CXCR6, XR1 and ABO involved with the severity of COVID-19 in indigenous people." (PMID 38543725, 2024). "SNP rs17078346 SLC6A20-LZTFL1 was linked with increased BMI (p = 0.01) and severe COVID-19 in obese individuals (risk allele C, OR = 1.72, 95% CI = 1.15–2.58, p = 0.01, (pbonf = 0.02))." (PMID 39175753, 2024). "A recent meta-analysis also demonstrated the role of the SLC6A20 gene (based on rs11385942) in severe COVID-19 outcomes." (PMID 36675784, 2023). "Known significant loci for COVID-19 severity in 3p21.31 (near SLC6A20 and LZTFL1) and 21q22.11 (in IFNAR2) were clearly replicated at genome-wide significance in this study, specifically for risk of infection, hospitalization and severity." (PMID 35708486, 2022). "Lastly, the four rare variants (two in the IRF7 gene, one in SLC6A20 gene and one in DDX58 gene) segregating in a patient with a severe phenotype of COVID-19 (family n°6), were all evaluated as “tolerated” with a CADD score <25." (PMID 36228008, 2022). "The correlation between SLC6A20 and poor clinical outcomes in COVID-19 patients is suspected to stem from its affinity for ACE2 because SLC6A20 was reported to interact with ACE2." (PMID 35021853, 2022). "The first COVID-19 genome-wide association study identified the 3p21.31 gene cluster, including “SLC6A20, LZTFL1, CCR9, FYCO1, CXCR6, and XCR1” as a genetic susceptibility locus in severe patients with COVID-19 and respiratory failure." (PMID 37521836, 2022). "We identified putative causal genes, including SLC6A20, CXCR6, CCR9, and CCR5 in the locus on 3p21.31, quantifying their effect on mediating expression and on severe COVID-19." (PMID 35318325, 2022). "The COVID-19 Host Genetics Initiative (HG1) report concurred with the association of variants in ABO, SLC6A20, TYK2, DPP9, IFNAR2, and additionally reported a variant in Protein Phosphatase 1 Regulatory Subunit 15A (PPP1R15A) in influencing COVID-19 severity." (PMID 36143338, 2022). "In July 2021, the COVID-19hg conducted an international meta-GWAS to increase the number of COVID-19 patients to 49,562, and newly reported the association of SLC6A20 with COVID-19 susceptibility and TYK2 with COVID-19 severity." (PMID 35264675, 2022). "Our genome-wide analysis of pneumonia and severe COVID-19 point to two overlapping regions (defined by linkage disequilibrium analysis), both of which include SLC6A20 and LZTFL1 genes." (PMID 35910207, 2022). "This study aimed to associate genetic variants in the SLC6A20, LZTFL1, CCR9, FYCO1, CXCR6, XCR1, and ABO genes with the risk of severe forms of COVID-19 in Amazonian Native Americans, and to compare the frequencies with continental populations." (PMID 35455670, 2022). "The eQTL analysis encompassing 22 lead SNPs identified 29 novel genes in addition to 4 genes (i.e., SLC6A20, FYCO1, CXCR6, CCR1) previously reported by the severe COVID-19 GWAS group to be associated with rs11385942 at locus 3p21.31." (PMID 34027315, 2021).
COVID-19 (continued). "Our findings identify SLC6A20 and CXCR6 as putative causal genes that modulate COVID-19 risk and highlight the usefulness of this integrative approach to bridge the divide between correlational and causal studies of human biology." (PMID 34425859, 2021). "An association study based on ~50,000 COVID-19 patients further supported the association of genetic variants in ABO, TYK2, DPP9, IFNAR2, SLC6A20 and Protein Phosphatase 1 Regulatory Subunit 15A (PPP1R15A) with the severity of COVID-19." (PMID 34575070, 2021). "Association between the overexpression of the SLC6A20 gene located at the 3p21.31 locus and encoding the transport protein for ACE-2 with the more severe course of COVID-19 was found." (PMID 33802310, 2021). "Also, recently, it was found that a region of our DNA situated on chromosome 3 (locus 3p21.31), spanning a length of 49.3 kb, consisting of 6 genes (SLC6A20, LZTFL1, CCR9, FYCO1, CXCR6, and XCR1), was associated with the risk of developing severe COVID-19." (PMID 37929242, 2023). "According to GeneAtlas, FYCO1 variant rs33910087 is a highly significant modifier of monocyte percentage (p = 3.85 × 10−46), and based on GTEx v8, this variant is also an eQTL for several protein-coding genes previously associated with COVID-19 (CXCR6, FYCO1, SLC6A20, CCR1, LZTFL1)." (PMID 35910207, 2022). "The present study investigated genetic variants in the SLC6A20, LZTFL1, CCR9, FYCO1, CXCR6, XCR1, and ABO genes that are potentially related to severe forms of COVID-19 in Amazonian Native American populations, and compared their frequencies with continental populations." (PMID 35455670, 2022). "Using WES data, we focused on nine genes that have been reported to be involved in the SARS-CoV-2 entry pathway (ACE2, RAB7B, ADAM17, TMPRSS2), host immune response (IFNAR2, TYK2), and/or were previously shown to be associated with COVID-19 outcomes (DPP9, LZTFL1, SLC6A20)." (PMID 36292769, 2022). "By integrating the results of CRISPR screen and cis-eQTLs, we have identified SLC6A20 and CXCR6 as potential protein-coding genes in the 3p21.31 locus through which noncoding variants associated with COVID-19 risk in human patients may function." (PMID 34425859, 2021). "The other chromosome 3 locus (bps 45637109–45839176) indexed by lead SNP rs73062389 (p = 2.6 × 10−17) contained a suggestive but non-significant association between SLC6A20 and COVID-19 positivity (p = 4.8 × 10−05)." (PMID 35222515, 2021). "We confirmed the existence of the 3p21.31 region (LZTFL1, SLC6A20) implicated in the susceptibility to SARS-CoV-2 infection and TYK2 gene might be involved in COVID-19 severity." (PMID 34945790, 2021). "This COVID-19 locus has its highest association signal over the SLC6A20 gene and does not overlap the CCR5 gene body." (PMID 34925370, 2021). "Our findings support the notion that some genetic variants, most notably at the ABO and PPP1R15A loci, in addition to SLC6A20, can indeed affect susceptibility to infection rather than progression to severe COVID-19 once infected." (PMID 34237774, 2021). "Our gene-based analyses also support the involvement of SLC6A20 in COVID-19 (p = 4.8 × 10−05)." (PMID 35222515, 2021). "deleted this portion of LZTFL1 using a genome editor CRISPR/Cas9 in blood cell lines and found that the expression of CCR9 and SLC6A20 was affected by the locus, suggesting that this COVID-19 GWAS locus at chromosome locus 3p21.21 may influence different genes depending on cell type." (PMID 34998241, 2022). "The first and most significant locus described in GWAS associated with COVID-19 critical is 3p21.31, which encompasses six genes (SLC6A20, LZTFL1, CCR9, FYCO1, CXCR6, and XCR1) (The Severe COVID-19 GWAS Group, 2020)." (PMID 38226654, 2024). "The strongest and most consistent finding for COVID-19 severity is the 3p21.31 region containing multiple protein-coding genes, including LZTFL1, SLC6A20, FYCO1, and chemokine receptor genes (CCR9, CXCR6 and XCR1)." (PMID 38517939, 2024).